RN7SKP104 (RN7SK pseudogene 104)
Gene: Miscellaneous RNA gene on chromosome 7 (97,598,933 to 97,599,260, reverse strand). Ensembl gene ENSG00000199475.
Homologues: Orthologues: chimpanzee 7SK (99% identical). Paralogues in human: 7SK (79% identical), RN7SKP187 (76% identical), RN7SKP48 (76% identical), RN7SKP174 (74% identical), RN7SKP185 (74% identical), RN7SKP227 (73% identical), RN7SKP118 (73% identical), RN7SKP62 (73% identical), RN7SKP178 (72% identical), RN7SKP292 (72% identical), RN7SKP76 (72% identical), RN7SKP55 (70% identical), and 284 more.